KCNQ2 (potassium voltage-gated channel subfamily Q member 2)
Diseases named in the same sentence as KCNQ2 in open-access papers (continued):
Sharing a sentence is not in itself a finding about the gene and the disease.
benign familial neonatal convulsion (4 papers, 2015 to 2023). "Potassium channel, voltage-gated, kqt-like subfamily, member 2 (KCNQ2) pathogenic variants cause benign neonatal epilepsy and KCNQ2-related encephalopathy." (PMID 34440332, 2021). "KCNQ3 and KCNQ2 gene mutations segregate with various forms of Kv7.3/Kv7.2-channelepsies such as benign familial neonatal convulsion (BFNC) and rolandic epilepsy." (PMID 25784856, 2015). "Mutations in the KCNQ2 and KCNQ3 genes, which encode Kv7.2 and Kv7.3 channels, respectively, have been identified as a cause of BFNE (benign familial neonatal epilepsy)." (PMID 37190119, 2023).
cognitive decline (4 papers, 2020 to 2025). "In fact, KCNQ2 has been associated with cognitive decline during normal aging, and M channel blockers have been proposed as potential therapeutic targets to treat cognitive decline in AD." (PMID 37605276, 2023). "KCNQ2 is expressed more highly in human hippocampus than in other brain regions, and KCNQ2 gene variants and expression analysis suggest it is associated with cognitive decline in normal aging." (PMID 34318654, 2021). "The role of the Kv7.2 channel in neurodegeneration is not the focus of this review; however, it is interesting to note that common genetic variation in KCNQ2 has recently been associated with risk of cognitive decline in healthy elderly." (PMID 33192566, 2020).
Cognitive impairment (4 papers, 2020 to 2025). Abnormal cognition is characterized by deficits in thinking, reasoning, or remembering. "Minimal disruption of memory in KCNQ2+/− mice, which lacks spontaneous seizures, is in sharp contrast to cognitive deficits induced by genetic ablation of IM in mice, which display spontaneous seizures." (PMID 35928789, 2022). "Since changes in gamma oscillation power may provide a disease biomarker to investigate novel therapies against cognitive impairment in diseases, the present data suggest that KCa2, KCNQ2/3, and T-type calcium channel modulators might be promising targets in these states." (PMID 35177966, 2021).
depression (4 papers, 2013 to 2023). "Arketamine and (2R,6R)-HNK increase the in vitro production of KCNQ2 mRNA (codes for potassium voltage-gated channel subfamily Q member 2) implicated in depression, in ventral hippocampus glutaminergic neurons, adding yet another potential mechanism of anti-depressant activity." (PMID 37242525, 2023). "A number of the selected hub genes in our study have been previously reported to be related to FMS or depression, including GRIK1&2, NGF, KCNQ2, GRIA1, TRPV4, IL1A, and GABAA receptors." (PMID 37065490, 2023).
schizophrenia (4 papers, 2012 to 2024). A major psychotic disorder characterized by abnormalities in the perception or expression of reality. "KCNQ2 phosphorylation may be a novel drug target for schizophrenia and Parkinson's disease associated with D2R-MSN dysfunction, as it is regulated downstream of dopamine and acetylcholine antagonist pathways." (PMID 38516040, 2024).
Tremor (4 papers, 2021 to 2025). An unintentional, oscillating to-and-fro muscle movement about a joint axis. "The identified variant, although of uncertain significance, may disrupt KCNQ2 function and also play a role in tremor pathogenesis." (PMID 38737299, 2024). "In this context, the KCNQ2 could be considered a candidate gene for tremor because it regulates neuronal excitability, synaptic transmission, and depolarization/ hyperpolarization of the membrane." (PMID 38737299, 2024).
benign familial neonatal seizures 1 (3 papers, 2020 to 2021). "As βIV-spectrin plays a role in the clustering of KCNQ2 subunit-containing potassium channels, there could be some degree of overlap of clinical symptoms with early-infantile epileptic encephalopathy type 7 and with benign familial neonatal seizures type 1." (PMID 33772159, 2021).
convulsion (3 papers, 2011 to 2019). A rapid and repeated body muscle contract that results in an uncontrolled shaking of the body. "KCNQ2/3 channels form the native M-current controlling excitability of most neurons, with mutations causing benign neonatal febrile convulsions." (PMID 21915266, 2011). "Loss of functions mutations in either KCNQ2 or KCNQ3 result in a form of epilepsy called benign neonatal febrile convulsions." (PMID 21915266, 2011). "Mutations in two family members, Potassium Voltage-Gated Channel Subfamily Q Member 2 (KCNQ2) and Potassium Voltage-Gated Channel Subfamily Q Member 3 (KCNQ3), have been correlated with inherited neonatal epilepsy, e.g., benign family neonatal convulsions." (PMID 31151179, 2019).
hearing loss (3 papers, 2014 to 2021). "In this study, we tested whether opening voltage-gated potassium channels using ICA-105665, a novel small molecule that opens KCNQ2/3 and KCNQ3/5 channels, can reduce salicylate-induced hearing loss." (PMID 25904892, 2015). "However, the function of KCNQ2/3 and KCNQ3/5 in salicylate-induced cochlear hearing loss is poorly understood." (PMID 25904892, 2015). "Therefore, we tested the effects of ICA-105665, a novel small molecule that selectively opens KCNQ2/3 and KCNQ3/5 channels (Kv7.2/7.3 and Kv7.3/7.5) to determine its effects on salicylate-induced hearing loss." (PMID 25904892, 2015).
infantile epilepsy (3 papers, 2020 to 2026). "Moreover, the most prevalent genetic diagnoses for infantile epilepsy, particularly for patients aged < 12 months, were KCNQ2, PRRT2, and SCN1A." (PMID 35720076, 2022). "Importantly, sodium channel blockers, such as OXC and carbamazepine, have proven to be efficacious in PRRT2- and KCNQ2-related infantile epilepsies." (PMID 35720076, 2022).
Pain (3 papers, 2021 to 2025). An unpleasant sensory and emotional experience associated with actual or potential tissue damage, or described in terms of such damage. "This reversal was not seen in the mice with KCNQ2 overexpression in the VTA-to-mPFC DA neurons, These results indicate that functional modulation of KCNQ2 channels in the VTA-to-NAc, rather than the VTA-to-mPFC circuit contributes to regulating thermal nociception in chronic neuropathic pain." (PMID 33900570, 2021).
tuberous sclerosis (3 papers, 2021 to 2023). Hereditary disease characterized by seizures, intellectual disability, developmental delay, and skin and ocular lesions. "For example, there are a number of trials including rapamycin/everolimus, targeting the mTOR pathway, for the treatment of tuberous sclerosis complex and related WS; retigabine for the treatment of KCNQ2-related WS; and topiramate for the treatment of CACNA1E-related WS." (PMID 34055682, 2021).
atypical Rett syndrome (2 papers, 2018 to 2022). A neurodevelopmental disorder that is diagnosed when a child presents with a Rett-like syndrome but does not fulfill all the diagnostic criteria for typical Rett syndrome (classic/typical RTT). "Genes, such as IQSEC2 and even KCNQ2 from the green node, are linked to these genes since both genes are involved in the Rett-like syndrome phenotype." (PMID 35813072, 2022).
benign familial infantile epilepsies (2 papers, 2018 to 2023). "KCNQ2 mutations associate with wide range of phenotypes: BFNIS, benign familial infantile seizures, neonatal onset epileptic encephalopathies, and ESESS/CSWSS." (PMID 29976148, 2018).
Brugada syndrome (2 papers, 2017 to 2025). A genetically heterogeneous condition characterized by complete or incomplete right bundle branch block accompanied by ST elevation in leads V1-V3. "The non-affected mother (I:2) had family history of Brugada syndrome and showed the variants in KCNQ2 and SCN1A genes." (PMID 29261713, 2017).
colorectal cancer (2 papers, 2021 to 2024). A primary or metastatic malignant neoplasm that affects the colon or rectum. "Downregulation of KCNQ2 was reported to be correlated with oxaliplatin-induced trigeminal neuropathic pain that occurs in the majority of advanced colorectal cancer patients receiving oxaliplatin-based chemotherapy, and the potentiator retigabine of KCNQ2 alleviated neuropathic pain in rat models." (PMID 38807370, 2024).
Down syndrome (2 papers, 2021 to 2024). "The autonomy of the couple was respected when they decided to opt for genome-wide tests where WES was anticipated to cover the information of the KCNQ2 variant (c.636C>G:p.D212E) and CMA to rule out diseases caused by CNVs, such as Down syndrome and DiGeorge syndrome." (PMID 34970295, 2021).
Dyskinesia (2 papers, 2022). A movement disorder which consists of effects including diminished voluntary movements and the presence of involuntary movements. "KCNQ2 mutations affect the protein expression and M-current in the cells of the midbrain and striatum, and this is also a crucial factor in dyskinesia after the age of 4 weeks." (PMID 35269516, 2022). "Neonatal seizures associated with severe neonatal myoclonus such as dyskinesia due to a familial KCNQ2 gene mutation was reported." (PMID 35269516, 2022).
early-onset epilepsy (2 papers, 2022 to 2023). "We assembled a de-identified panel of disease-implicated KCNQ2 variants from databases of individuals with early-onset epilepsy and/or neurodevelopmental impairment participating in research, individuals undergoing clinical genetic testing, and variants described in prior publications." (PMID 35104249, 2022).
focal epilepsy (2 papers, 2019 to 2024). A seizure caused by a localized disorder. "Although focal epilepsy has been widely reported to be associated with KCNQ2 variants, to our knowledge, a detailed phenotype with strict auditory features has never been reported." (PMID 39796146, 2024).
generalized tonic-clonic seizures (2 papers, 2020 to 2021). "A boy had a neonatal epileptic encephalopathy with generalized tonic-clonic seizures associated with the heterozygous mutation c.619C > T (p.Arg207Trp) in KCNQ2 (potassium voltage-gated channel subfamily Q member 2)." (PMID 33806661, 2021).
idiopathic generalized epilepsy (2 papers, 2010 to 2013). A generalised epilepsy that encompasses several common seizure phenotypes including childhood absence epilepsy, juvenile absence epilepsy, juvenile myoclonic epilepsy and epilepsy with generalized tonic-clonic seizures alone. "Mutations in the genes KCNQ2 and KCNQ3 cause idiopathic generalized epilepsy (IGE)." (PMID 23596459, 2013). "The molecular identity that underlies the M-current was discovered as a result of identification of mutations in human potassium channel subunits referred to as KCNQ2 (Kv7.2) and KCNQ3 (Kv7.3) from idiopathic generalized epilepsy patients." (PMID 20796319, 2010).
status epilepticus (2 papers, 2020 to 2022). Status epilepticus is defined as a continuous seizure lasting more than 30 min, or two or more seizures without full recovery of consciousness between any of them. "Rather, it could arise from hyperexcitability of the temporal lobe involved in passive IA because KCNQ2+/− mice show a heightened seizure susceptibility against kainic acid, which induces status epilepticus arising from the temporal lobe." (PMID 35928789, 2022).
angiosarcoma (1 paper, 2016). A malignant tumor arising from the endothelial cells of the blood vessels. "Notably, expression of several potassium channels is modified in bladder cancer vessels vs controls (KCNC4, KCNG4, KCNS2) and in angiosarcoma vs controls (namely KCNJ16, KCNQ2, KCNJ15, KCNJ12, KCNJ1)." (PMID 27716384, 2016).
arthropathy (1 paper, 2025). Any disorder of the joints. "We suggest testing patients who are negative for common disease‐causing variants in SeLFIE (SCN2A, SCN8A, KCNQ2, PRRT2) for the ANKH c.‐11C>T change, especially if there is evidence for a familial arthropathy." (PMID 40574727, 2025).
autosomal dominant nocturnal frontal lobe epilepsy (1 paper, 2010). A seizure disorder characterized by intermittent dystonia and/or choreoathetoid movements that occur during sleep. "Mutations in KCNQ2 and CHRNA4 have been identified in individuals with benign familial neonatal convulsions (BFNC) and autosomal dominant nocturnal frontal lobe epilepsy (ADNFLE), respectively." (PMID 20805988, 2010).
brain malformations (1 paper, 2021). "The ratio was highest in 6 (85.7%) of the 7 patients with genetic seizures (6 are KCNQ2 seizures, 1 is GABRB3); 15 (36.6%) of the 41 cases of HIE; 3 (30%) of the 10 cases with congenital structural brain malformations; 4 (57.1%) of the 7 hypocalcemic or hypoglycemic seizures." (PMID 34414144, 2021).
Cirrhosis (1 paper, 2024). A chronic disorder of the liver in which liver tissue becomes scarred and is partially replaced by regenerative nodules and fibrotic tissue resulting in loss of liver function. "Cirrhosis selectively modulates KCNQ2 transcript expression, potentially affecting KM currents in both SG and ICG neurons—a modulation also noted in cardiac efferent neurons of TBI rat models." (PMID 39200187, 2024).
cortical dysplasia (1 paper, 2023). "Remaining 19 patients had non-specific changes on MRI.The 16 malformative patients also included a child with KCNQ2 mutation with a focal cortical dysplasia." (PMID 38074073, 2023).
developmental and epileptic encephalopathy, 33 (1 paper, 2022). Any early infantile epileptic encephalopathy in which the cause of the disease is a mutation in the EEF1A2 gene. "These clinical features are similar to BFNE caused by KCNQ2 variations and are different from those of autosomal-dominant nocturnal frontal lobe epilepsy (ADNFLE) caused by CHRNA4 variations and developmental and epileptic encephalopathy 33 (DEE33) caused by EEF1A2 variations." (PMID 35557555, 2022).
diabetic ketoacidosis (1 paper, 2018). The metabolic condition resulted from uncontrolled diabetes mellitus, in which the shift of acid-base status of the body toward the acid side because of loss of base or retention of acids other than carbonic acid is accompanied by the accumulation of ketone bodies in body tissues and fluids. "It is also interesting to speculate a role for BHB activation of KCNQ2/3 channels in the anticonvulsant effects of the ketogenic diet, given that BHB is the first ketone body produced during fasting or ketogenic diets, and also in diabetic ketoacidosis." (PMID 29748663, 2018).
gastric adenocarcinoma (1 paper, 2023). "Comparing the transcriptomes of isolated Prom1+ gastric stem cells and their Prom1− daughter cells from normal gastric mucosa and gastric adenocarcinomas, we observe that KCNQ1 is down-regulated and KCNQ2/3/5 genes are significantly up-regulated (Q < 0.05) in gastric adenocarcinomas in this model." (PMID 37748809, 2023).
generalized dystonia (1 paper, 2022). "In eight patients with generalized dystonia from infancy, the mutation of PIGA, TCF4, CHRNG, SLC16A2, KCNQ2, NACC1, CTNNB1, or ARSA gene were found to be causative." (PMID 35719373, 2022).
Hypocalcemia (1 paper, 2021). An abnormally decreased calcium concentration in the blood. "The interictal aEEG findings revealed relatively better background in most seizures related to non-structural etiologies revealed by an MRI, such as hypocalcemia and KCNQ2 EE, compared with the seizures linked to those with other etiologies." (PMID 34414144, 2021). "The non-structural etiologies, such as hypocalcemia and neonatal KCNQ2 seizures, had a specific feature that could help differentiate the EEG of these seizures from the other etiologies." (PMID 34414144, 2021).
lung adenocarcinoma (1 paper, 2022). A carcinoma that arises from the lung and is characterized by the presence of malignant glandular epithelial cells. "The results showed that ACAN, CDKN3, GRIN2A, IL17A, KCNQ2, TIMP1, and UCHL1 were significantly up-regulated in lung adenocarcinoma cells." (PMID 36147496, 2022).
MELAS (1 paper, 2021). "Additionally, we identified heterozygous KCNQ1 mutation c.575G > A (p.Arg192His) and heterozygous KCNQ2 mutation c.598C > A (p.Leu200Met) in one MELAS patient (P9)." (PMID 33484326, 2021).
methamphetamine dependence (1 paper, 2025). A drug dependence that is a psychological dependency on the regular use of methamphetamine. "Methylation levels in CG sites in CES1 showed high diagnostic accuracy (AUC = 0.755) for methamphetamine dependence, while the AUC values for KCNQ2 and USP7 were 0.68 and 0.664, respectively, indicating moderate classification." (PMID 41368944, 2025). "Additionally, the methylation level of CG2 in the KCNQ2 gene was significantly associated with methamphetamine dependence (p = 0.003), yielding an AUC of 0.68 (95% CI: 0.568–0.792), a sensitivity of 0.40 and a specificity of 0.92." (PMID 41368944, 2025). "Notably, the observed hypomethylation of GABRB1, and KCNQ2, along with the hypermethylation of CES1 and USP7, may underlie the pathophysiology of methamphetamine dependence." (PMID 41368944, 2025).
osteoarthritis (1 paper, 2021). A noninflammatory degenerative joint disease occurring chiefly in older persons, characterized by degeneration of the articular cartilage, hypertrophy of bone at the margins and changes in the synovial membrane. "Consistent with use of tannic-acid containing, KCNQ2/3-activating plants as topical analgesics, others previously found that tannic acid is effective as a topical agent for improvement burn wound healing and reducing burn pain, and for osteoarthritis." (PMID 34858215, 2021).
sleep disorder (1 paper, 2022). A change from the patient's baseline sleeping pattern, in the hours slept and/or an alteration/dysfunction in the stages of sleep. "The pharmacological remedy of sleep disruption by targeting Kcnq2/3 channels could be a promising therapeutic strategy for improving sleep quality and preventing aging-related sleep disorders." (PMID 35840555, 2022). "Therefore, it is of importance to carry out the study on older adults who suffer from sleep disorders to verify whether there is an altered level of Kcnq2/3 in the Hcrt neuron." (PMID 35840555, 2022).
ventricular tachycardia (1 paper, 2020). A disorder characterized by an electrocardiographic finding of three or more consecutive complexes of ventricular origin with a rate greater than a certain threshold (100 or 120 beats per minute are commonly used). "Here we report a case of KCNQ2-related neonatal epileptic encephalopathy (KCNQ2-NEE) that is complicated by an incidentally found ventricular tachycardia." (PMID 32362866, 2020).
neurodevelopmental disorder (9 papers, 2020 to 2026). A behavioral and cognitive disorder with onset during the developmental period that involves impaired or aberrant development of intellectual, motor, or social functions. "Loss-of-function KCNQ2 variants lead to severe neurodevelopmental disorders that present soon after birth." (PMID 33863780, 2021). "KCNQ2 is the second most frequently mutated gene in neurodevelopmental disorder characterized by cognitive and behavioral deficits." (PMID 33071824, 2020). "The best proof for a role of the M-current in neurodevelopment is the observation that pathogenic variants in KCNQ2 are responsible for a spectrum of neurodevelopmental disorders in humans." (PMID 33192566, 2020). "KCNQ2 channels were the second members of this family to be identified, with a rich history relating to neurodevelopmental disorders." (PMID 33863780, 2021). "Moreover, GOF of KCNQ2 and KCNQ3 leads to neurodevelopmental disorders with no established treatments, while LOF (KCNQ2 and KCNQ3) causes neuronal hyperexcitability or neonatal seizures." (PMID 41155561, 2025).
neurological disorders (8 papers, 2016 to 2025). "Mutations in KCNQ2 are linked to various neurological disorders, including neonatal-onset epilepsy." (PMID 39971736, 2025). "This system was employed to inactivate two genes associated with neurological disorder (TSC2 and KCNQ2) and achieved up to 85% efficiency of gene targeting in the differentiated cells." (PMID 27857203, 2016).